CPEB1 (cytoplasmic polyadenylation element binding protein 1)
Description:
Sequence-specific RNA-binding protein that regulates mRNA cytoplasmic polyadenylation and translation initiation during oocyte maturation, early development and at postsynapse sites of neurons. Binds to the cytoplasmic polyadenylation element (CPE), an uridine-rich sequence element (consensus sequence 5'-UUUUUAU-3') within the mRNA 3'-UTR. RNA binding results in a clear conformational change analogous to the Venus fly trap mechanism. In absence of phosphorylation and in association with TACC3 is also involved as a repressor of translation of CPE-containing mRNA; a repression that is relieved by phosphorylation or degradation (By similarity). Involved in the transport of CPE-containing mRNA to dendrites; those mRNAs may be transported to dendrites in a translationally dormant form and translationally activated at synapses (By similarity). Its interaction with APLP1 promotes local CPE-containing mRNA polyadenylation and translation activation (By similarity). Induces the assembly of stress granules in the absence of stress. Required for cell cycle progression, specifically for prophase entry.
Synonyms: CPE-BP1; h-CPEB; hCPEB-1; CPEB; FLJ13203; CPEB-1
Tractability: PROTAC: ubiquitination databases record sites on it.
Gene: Protein-coding gene on chromosome 15 (82,543,201 to 82,648,861, reverse strand). Ensembl gene ENSG00000214575.
Subcellular location: Cytoplasm; Nucleus; Cytoplasm, P-body; Cytoplasmic granule; Synapse; Membrane; Postsynaptic density; Cell projection, dendrite
Subcellular location (Human Protein Atlas): Cytosol; Nucleoplasm
Gene Ontology:
Molecular function: protein binding; mRNA 3'-UTR AU-rich region binding; mRNA 3'-UTR binding; mRNA regulatory element binding translation repressor activity; ribosome binding; translation factor activity, RNA binding; nucleic acid binding; RNA binding; translation regulator activity
Biological process: cellular response to hypoxia; cellular response to insulin stimulus; negative regulation of cytoplasmic translation; regulation of mRNA 3'-end processing; cellular response to amino acid stimulus; negative regulation of translation; regulation of translation; translation
Cellular component: cytoplasm; cytosol; nucleoplasm; nucleus; neuron projection; synapse; dendrite; membrane; P-body; postsynaptic density
Genetic constraint (gnomAD): Loss-of-function variants: 5 observed, 59.3 expected, observed/expected ratio (o/e) 0.0843, 90% interval 0.043 to 0.18. The upper end of that interval is the gene's LOEUF score, 0.18, which puts it in group 1 of 6, group 1 being the genes least tolerant of losing a copy. Missense variants: 518 observed, 714.5 expected, observed/expected ratio (o/e) 0.72, 90% interval 0.67 to 0.78. Synonymous variants: 254 observed, 263.24 expected, observed/expected ratio (o/e) 0.96, 90% interval 0.87 to 1.07.
Homologues: Orthologues: chimpanzee CPEB1 (95% identical), pig CPEB1 (92% identical), guinea pig CPEB1 (91% identical), dog CPEB1 (91% identical), mouse Cpeb1 (90% identical), rat Cpeb1 (90% identical), rabbit CPEB1 (85% identical), macaque RPS17 (78% identical), tropical clawed frog cpeb1 (78% identical), zebrafish cpeb1b (62% identical), zebrafish cpeb1a (47% identical), Drosophila melanogaster orb (39% identical), and 1 more. Paralogues in human: CPEB2 (29% identical), CPEB3 (28% identical), CPEB4 (27% identical).
Diseases named in the same sentence as CPEB1 in open-access papers:
CPEB1 is named in the same sentence as 72 diseases in open-access papers, as found by Europe PMC text mining. Sharing a sentence is not in itself a finding about the gene and the disease. The quoted sentences say what the papers report.
breast carcinoma (12 papers, 2017 to 2022). "The risk score of breast cancer patients was calculated using the following formula: Risk score = −0.482 * expression of CPEB1 + 0.468 * expression of NOTCH3 + 0.213 * expression of NUAK1 + 0.321 * expression of PDPK1." (PMID 36072578, 2022). "Among significantly downregulated genes with promoter hypermethylation, CDON, ID4, and CPEB1 were associated with neuroblastoma, breast cancers, and hepatocellular carcinoma, respectively." (PMID 31796082, 2019). "CPEB1 absence in breast cancer not only leads to the loss of polarity of mammary epithelial cells but also lengthens poly(A) and increases the polyadenylation and translation efficiency of MMP9 mRNA (tumor metastasis-promoting factor), which promotes the metastasis of breast cancer." (PMID 36052258, 2022). "In breast cancer, cytoplasmic polyadenylation element-binding protein 1 (CPEB1) mediates EMT and metastasis by enhancing the shortening of the polyA tail of MMP9, which lowers MMP9 translation." (PMID 36076302, 2022). "The loss of CPEB1 results in poly(A) tail lengthening and increased translation of the mRNA for MMP9 in breast cancer cells." (PMID 32967226, 2020). "miR-129-3p has been reported to implicate in breast cancer cell apoptosis, and CPEB1 inhibition could suppress oxidative stress, inflammation, and apoptosis in oxidized low-density lipoprotein–induced endothelial dysfunction." (PMID 33228708, 2020). "CPEB1 has an inverse correlation with metastasis of breast cancer." (PMID 32967226, 2020). "Moreover, studies have shown that cytoplasmic polyadenylation element binding protein 1 (CPEB1) inhibits breast cancer metastasis by reducing the expression of matrix metallopeptidase 9 (MMP9) mRNA." (PMID 31514467, 2019). "Similarly, CPEB1 mediates epithelial-to-mesenchyme transition in breast, and mice depleted of this gene showed increased breast cancer metastatic potential." (PMID 29914366, 2018). "In addition, the expression levels of CPEB1, NOTCH3, NUAK1, and PDPK1 were significantly discrepant among the molecular subtypes of breast cancer." (PMID 36072578, 2022).
melanoma (12 papers, 2010 to 2025). A malignant, usually aggressive tumor composed of atypical, neoplastic melanocytes. "For instance, in melanoma, miR-455-5p progressed melanoma metastasis by targeting CPEB1, a well-established tumor suppressor." (PMID 38911375, 2024). "By contrast, decreased RNA editing of miR-455-5p in melanoma allows for downregulation of tumor suppressor CPEB1 and promotes tumor progression." (PMID 32157211, 2020). "In melanoma, loss of ADAR1 expression can lead to abnormal miRNA processing or functioning and changes in the total mature levels of miR-455-5p, contributing to melanoma growth and metastasis via downregulation of the tumor suppressor gene CPEB1." (PMID 32273831, 2020). "In melanoma, unedited miR-455-5p promotes cancer growth and metastasis by inhibiting the tumour suppressor gene cytoplasmic polyadenylation element binding protein 1 (CPEB1)." (PMID 31547885, 2019). "A recent study in melanoma identified that miR-455-5p has two A-to-I editing sites in low metastatic melanomas and this changed its inhibitory effect on its target, the tumor suppressor gene, CPEB1." (PMID 30018188, 2018). "For example, only the WT form of miR-455-5p binds and inhibits the expression of the tumor suppressor gene CPEB1, thus contributing to melanoma metastasis." (PMID 29386624, 2018). "As the case of melanomas, melanocytes also expressed CPEB1, CPEB2 and CPEB3, but these proteins appear to be unable to compensate for CPEB4 depletion." (PMID 27857118, 2016). "Indeed, miR-455-5p WT but not the edited form specifically targets the tumor suppressor gene CPEB1, thus contributing to melanoma metastasis." (PMID 29386624, 2018). "Indeed, WT miR-455-5p preferentially binds and inhibits the expression of the tumor suppressor gene CPEB1, thus contributing to melanoma metastasis." (PMID 29386624, 2018). "It has been reported that miR-455-5p promoted melanoma metastasis by inhibiting CPEB1." (PMID 29383133, 2017). "As a previous study showed that miR-455-5p inhibits the tumor suppressor gene CPEB1 expression to facilitate melanoma metastasis, we next test whether the targeting of SOCS3 by miR-455-5p is important for NSCLC." (PMID 29383133, 2017). "Indeed, our data revealed that melanomas -as other tumour types- express other CPEB family members (particularly CPEB1 and CPEB2), which could have acted in a compensatory manner in the absence of CPEB4." (PMID 27857118, 2016). "26% of the expression variation of CPEB1 that regulates synaptic plasticity and is implied in cancer development and GRM1 that is involved in neurotransmitter in the central nervous system and implicated in melanoma was explained by overexpressed mir-25 and mir-15b, respectively." (PMID 21114830, 2010). "Mining solid tumours in the CCLE (N=853), and validating mRNA levels experimentally by qRT-PCR (N=20), we found however CPEB1 and CPEB2 to be well expressed in melanomas, with levels even higher than for the majority of solid tumours analysed." (PMID 27857118, 2016).
glioblastoma (10 papers, 2016 to 2025). The most malignant astrocytic tumor (WHO grade IV). "In glioblastoma cells, cytoplasmic polyadenylation element binding protein 1 (CPEB1) increases AEG-1 translation by binding to its mRNA, while in HCC cells CPEB3 inhibits AEG-1 translation by binding to the 3′-untranslated region of AEG-1 mRNA." (PMID 40282551, 2025). "Glioblastoma multiforme, the most common and aggressive brain tumor, has a significantly reduced level of CPEB1 gene expression as compared with normal brain cells." (PMID 33789753, 2021). "Induction of CPEB1 expression upon transfection of a glioblastoma cell culture with a plasmid results in a two-fold reduction in the rate of cell proliferation." (PMID 33789753, 2021). "Most of the astrocytoma specimens showed staining for CPEB1 (26/29: 8/8 AII and 18/21 AAIII), while 23/32 glioblastoma (6/7 sGBM and 17/25 pGBM) samples contained CPEB1 positive cells." (PMID 27256982, 2016). "This leads to higher levels of p27Kip1 in the cell, in turn significantly inhibiting cell proliferation, and confers to CPEB1 a potential value as a tumor suppressor in Glioblastoma." (PMID 27142352, 2016). "The multipathway activity assay carried out to investigate the influence of CPEB1 overexpression on the activity of cancer-associated signaling pathways, revealed an upregulation of estrogen, hedgehog, HNF4 and TGFβ pathways in glioblastoma cells." (PMID 27256982, 2016). "Of note, CPEB1 may also inhibit glioblastoma growth via its capacity to promote poly-A tail elongation and translation of the cell cycle inhibitor, p27." (PMID 33892791, 2021). "In the present study, we show that CPEB1 is significantly downregulated in human Glioblastoma Multiforme (GBM) tissues and that the restoration of its expression impairs glioma cell lines growth." (PMID 27142352, 2016). "In addition, all investigated glioblastoma cell lines showed hypermethylation of the CPEB1 gene." (PMID 27256982, 2016). "It was documented that cytoplasmic polyadenylation element-binding protein 1 (CPEB1) binds to AEG-1 mRNA and increases its translation in glioblastoma cells." (PMID 33918653, 2021). "Similarly, down-regulation of miR-101 in glioblastoma cells promotes their proliferation and invasion along with angiogenesis by increasing the EZH2-mediated overexpression of cytoplasmic polyadenylation element-binding protein 1 (CPEB1)." (PMID 27793053, 2016). "Furthermore, ectopic expression of a dominant-negative form of CPEB1 that does not induce polyadenylation limits the production of metadherin (MRDH), a metastasis-promoting factor, and reduces migration and tumor formation of glioblastoma cells." (PMID 36131924, 2022).
glioma (9 papers, 2014 to 2023). A benign or malignant brain and spinal cord tumor that arises from glial cells (astrocytes, oligodendrocytes, ependymal cells). "The observed methylation pattern shows that CPEB1 belongs to the genes affected by the glioma associated CpG island methylator phenotype (G-CIMP) in IDH1/2 mutant tumors." (PMID 27256982, 2016). "Downregulation of CPEB1 on the transcript as well as protein level was associated with a rising grade of glioma malignancy." (PMID 27256982, 2016). "For example, hypomethylation of cytoplasmic polyadenylation element-binding protein 1 (CPEB1), in our gene list, can be used as a potential glioma prognostic marker." (PMID 35677637, 2022). "Numerous reports have documented a role for CPEB1 in the development of gastric cancer, breast cancer, glioma, and hepatocellular carcinoma." (PMID 33892791, 2021). "Our previous studies showed that the expression of CPEB1 was increased in glioma tissues compared with normal brain tissues." (PMID 28252647, 2017). "In the present study, we found that CPEB1 is significantly downregulated in human gliomas and that the restoration of its expression impairs GBM cell lines growth." (PMID 27142352, 2016). "Decreased expression of CPEB1 protein in gliomas correlated with the rising grade of tumor malignancy." (PMID 27256982, 2016). "Here, we localized a DNA fragment upstream of the CPEB1 gene and developed a pyrosequencing assay to quantitatively assess the methylation of this position in a cohort of 63 human glioma specimens obtained from the German Brain Tumor Reference Center." (PMID 27256982, 2016). "This ultimately leads to altered epigenetic marks e.g. the glioma hypermethylator phenotype (G-CIMP) Besides CPEB1, we only observed altered methylation of a few CpG sites in the CPEB3 gene." (PMID 27256982, 2016). "To examine the possible role of CPEB1 in glioma malignancy, we analyzed the expression profile from the REMBRANDT (REpository for Molecular BRAin Neoplasia DaTa) database." (PMID 25216517, 2014). "Overexpression of CPEB1 decreased the number of GSCs in an orthotopically implanted glioma animal model." (PMID 25216517, 2014). "Overall survival was significantly longer in glioma patients with intermediate than low levels of CPEB1 expression (p = 0.0111)." (PMID 25216517, 2014). "Due to the downregulation of CPEB1 expression in human gliomas, we assayed the levels of CPEB1 expression in patient-derived GSCs cultured in serum-free stemness and serum-containing differentiation media." (PMID 25216517, 2014). "Hypermethylation of CPEB1 was observed in gliomas containing a mutant IDH1 gene." (PMID 27256982, 2016). "Furthermore, expression of CPEB1 transcript was studied in 6 normal brain and 25 glioma samples by sqRT-PCR." (PMID 27256982, 2016). "We observed decrease of CPEB1 protein expression with rising grade of glioma malignancy." (PMID 27256982, 2016). "Obviously, beside DNA methylation other mechanisms may be relevant for transcriptional repression of CPEB1 in gliomas." (PMID 27256982, 2016). "The overall survival of glioma patients positively correlated with the level of CPEB1." (PMID 25216517, 2014). "CPEB1 induced differentiation of GSCs in mouse glioma model." (PMID 25216517, 2014). "The expression profile of CPEB1 negatively correlated with overall survival in glioma patients." (PMID 25216517, 2014). "Furthermore, reports on the expression and the function of CPEB1 in glioma are inconsistent." (PMID 38158431, 2023). "Interestingly, recent studies have demonstrated that a number of microRNAs (miRNAs), which function as major regulators of post‐transcriptional mRNA expression, can modulate Cpeb1 expression by interacting with the Cpeb1 3’UTR in glioma, during mammalian spermatogenesis, and in neurons." (PMID 34480525, 2022).
glioma (continued). "Expression of the CPEB1 and CPEB4 genes influences the formation of gliomas in the brain." (PMID 33789753, 2021). "Unlike with CPEB1, expression of CPEB4 is increased in gliomas." (PMID 33789753, 2021). "Moreover, the level of CPEB1 mRNA is lower in gliomas (astrocytomas, oligodendrocytomas, and GBM) than in non-tumor brain tissue, further suggesting that CPEB1 plays a role as a tumor suppressor in glioma by inducing the differentiation of GSCs." (PMID 25216517, 2014).
gastric cancer (7 papers, 2016 to 2024). A primary or metastatic malignant neoplasm involving the stomach. "In gastric cancer (GC) cells, CPEB1 has been shown to enhance erastin-induced ferroptosis, a form of iron-dependent cell death." (PMID 39534397, 2024). "Ovarian and gastric cancer, as well as breast, myeloma, and colorectal cancer cell lines all display dampened CPEB1 expression." (PMID 33146632, 2020). "Two research teams reported the CPEB1 down-expression phenotype in gastric carcinoma and bone marrow mesenchymal stem cells." (PMID 27271671, 2016). "In addition, there are limited data on the role of CPEB1 in ferroptosis, just one study reported that CPEB1 promotes ferroptosis susceptibility in gastric cancer by suppressing TWIST1 expression 25, which does not apply to pancreatic cancer." (PMID 38904009, 2024). "To further assess the ubiquity of the axis in cancer, we overexpressed CPEB1 in multiple cancer cell lines and confirmed that p62 and NRF2 were downregulated in pancreatic and colorectal cancer, while no change was observed in gastric cancer." (PMID 38904009, 2024).
colorectal cancer (6 papers, 2014 to 2024). A primary or metastatic malignant neoplasm that affects the colon or rectum. "High methylation of the CPEB1 promoter, restricting chromatin accessibility and transcription factor binding, diminishes its expression, thereby influencing colorectal cancer progression." (PMID 38994352, 2024). "Decreased CPEB1 expression frequently occurs in ovarian and gastric tumors, as well as in breast, myeloma, and colorectal cancer cell lines." (PMID 33146632, 2020). "Levels of CPEB1 are also decreased in other types of human tumors, including myeloma, gastric, breast, ovarian, and colorectal cancers." (PMID 25216517, 2014). "Research into colorectal cancer metastasis has revealed a novel tumor-suppressive role for CPEB1." (PMID 38994352, 2024). "DNA hypermethylation promotes metastasis of colorectal cancer by regulating the binding of CEBPB and TFCP2 to CPEB1 promoters." (PMID 37771430, 2023).
astrocytoma (5 papers, 2014 to 2018). "Our recent study showed that the lncRNA CASC2c directly bound miR-101 and influenced miR-101 to mature, and CASC2c acted as a competing endogenous RNA (ceRNA) of miR-101 to competitively regulate CPEB1 and promote the malignant growth of astrocytoma." (PMID 30034397, 2018). "PRDM16, LMO3 and CPEB1 are hypomethylated genes in astrocytoma cells and because CPEB1 and LMO3 have been confirmed as epigenetic targets of miR-101, we examined the effects of miR-101 on the methylation status of PRDM16 by BSP." (PMID 26701852, 2016). "Our studies have shown that miR-101 can induce cell apoptosis or senescence by direct or epigenetic regulation to decrease the high expression levels of hypomethylated LMO3 or CPEB1 in astrocytoma cells." (PMID 26701852, 2016). "Our data have verified four new hypomethylated genes, F10, POTEH, LMO3 and CPEB1, and their prognostic values in astrocytomas." (PMID 26701852, 2016). "However, in the astrocytoma, because of the abnormally high expression of CASC2c, or aberrant low expression of miR-101 or the overexpression of CPEB1 as a result of hypomethylation status of its promoter, the balance of this regulatory complex of CASC2c, miR-101 and CPEB1 was broken." (PMID 28252647, 2017). "CPEB1 expression was significantly lower in tumor samples from 148 patients with astrocytoma, 67 with oligodendroglioma, and 228 with GBM, than in 28 non-tumor brain tissue samples." (PMID 25216517, 2014).